COPA (coat protein complex I subunit alpha)
Diseases named in the same sentence as COPA in open-access papers (continued):
Sharing a sentence is not in itself a finding about the gene and the disease.
cervical cancer (3 papers, 2022 to 2025). A primary or metastatic malignant neoplasm involving the cervix. "We demonstrated that deficiency of COPA dramatically interfered the aggressive behaviors of cervical cancer cells in vitro." (PMID 34991628, 2022). "Furthermore, we demonstrated moderate (score 2) or strong (score 3) IHC staining for COPA was a unfavorable independent risk factor for cervical cancer." (PMID 34991628, 2022). "In cervical cancer COPA was proposed as a potential prognostic biomarker, based on the association of its moderate/strong expression with unfavorable prognosis." (PMID 40978486, 2025). "We found that all tissues of AC and most tissues of SCC with stage II and above tumors were strongly positive stained of COPA (score 3), while a considerable number of tissues from patients with stage I cervical cancer were weakly stained for COPA (score 1)." (PMID 34991628, 2022). "Our results of IHC analysis demonstrated that COPA protein level was significantly elevated in advanced cervical cancer." (PMID 34991628, 2022). "COPA was identified as a potential prognostic biomarker for cervical cancer, which was additionally verified by IHC staining." (PMID 34991628, 2022). "The results indicated that moderate (score 2) or strong (score 3) staining of COPA, advanced stage and lymph node metastasis were unfavourable prognostic factors of cervical cancer." (PMID 34991628, 2022). "Subsequently, the expression of COPA protein in cervical cancer tissues was additionally verified in IHC cohort." (PMID 34991628, 2022). "Third, although we confirmed in vitro that COPA is an attractive pharmacological intervention target for cervical cancer, in vivo intervention experiments are also warranted in the future." (PMID 34991628, 2022). "So far, we have identified COPA as a potential prognostic biomarker and a pharmacological intervention target for cervical cancer on multiple levels." (PMID 34991628, 2022). "Second, the signalling mechanisms of COPA in cervical cancer is interpreted based on bioinformatics analyses, further experimental studies to validate our findings are imperative." (PMID 34991628, 2022). "We also identified COPA is a potential pharmacological intervention target of cervical cancer by a series of in vitro experiments." (PMID 34991628, 2022). "By retrospective IHC analysis, we additionally verified the proteomics results and demonstrated moderate or strong IHC staining for COPA is an unfavourable independent prognostic factor for cervical cancer." (PMID 34991628, 2022). "Notable, the critical functional role of COPA in cervical cancer was determined via in vitro experiments." (PMID 34991628, 2022). "We observed the effects of COPA on cell viability and tumorigenic ability in the two COPA knockdown cervical cancer cells." (PMID 34991628, 2022). "Together, we are the first to report COPA can serve as a potential prognostic biomarker and pharmacological intervention target for cervical cancer." (PMID 34991628, 2022). "Based on quantification of the following two unique peptides: GITGVDLFGTTDAVVK and CPLSGACYSPEFK, COPA was verified as a potential biomarker of cervical cancer via targeted proteomics." (PMID 34991628, 2022). "We additionally verified the expression of COPA in a large number of clinical samples of cervical cancer using IHC analysis." (PMID 34991628, 2022). "In untargeted (“discovery”) proteomics and targeted (“verification”) proteomics, COPA was consistently identified as a potential prognostic biomarker of cervical cancer." (PMID 34991628, 2022). "COPA protein was retrospectively evaluated in a larger cohort of patients with cervical cancer using IHC analysis, 140 patients were successfully scored for COPA staining." (PMID 34991628, 2022). "First, we retrospectively analysed the correlation between the IHC staining of COPA and clinicopathological characteristics of patients with cervical cancer, its clinical utility would be more convincing using prospective data to assess." (PMID 34991628, 2022).
cervical cancer (continued). "We identified COPA is a potential prognostic biomarker for cervical cancer in quantitative proteomics analysis." (PMID 34991628, 2022). "Moreover, COPA knock-down inhibits viability and tumorigenicity of cervical cancer cells, thus proposing it as a novel therapeutic target." (PMID 40978486, 2025). "Since, our previous analysis showed that the level of COPA protein was significantly increased in advanced cervical cancer, we also speculated that COPA could be an attractive pharmacological intervention target of cervical cancer." (PMID 34991628, 2022). "To this end, we explored COPA functional role in two cervical cancer cell lines." (PMID 34991628, 2022). "They found that S100A9, eEF1A1, PKM2, COPA and so on, may become candidate markers for early diagnosis of cervical cancer and new targets for therapy." (PMID 36498728, 2022). "We found that the median age of patients with low expression of COPA was similar in the two pathological types of cervical cancer, but the median age of patients with moderate (score 2) and strong (score 3) expression of COPA in cervical AC were relatively younger than that of in cervical SCC." (PMID 34991628, 2022). "High expressed COPA protein may also be an unfavorable prognostic factor of patients with cervical cancer." (PMID 34991628, 2022). "Finally, through a series of in vitro experiments, the notable contribution of COPA to the progression of cervical cancer was verified in two cervical cancer cell lines." (PMID 34991628, 2022). "Therefore, COPA is critical in the progression of cervical cancer." (PMID 34991628, 2022). "This study is the first to demonstrate that COPA may contribute to progression of cervical cancer." (PMID 34991628, 2022). "Therefore, we can speculate that high expressed COPA protein may also be an unfavorable prognostic factor of patients with cervical cancer." (PMID 34991628, 2022). "However, the function of COPA in cervical cancer is unknown." (PMID 34991628, 2022). "Three (2.1%) sample was negative (score 0) stained for COPA in the cervical cancer sample." (PMID 34991628, 2022).
glioma (3 papers, 2022 to 2025). A benign or malignant brain and spinal cord tumor that arises from glial cells (astrocytes, oligodendrocytes, ependymal cells). "Similarly, circCOPA encodes COPA-99AA, a protein that inhibits glioma-cell proliferation, migration, and invasion by disrupting the NONO-SFPQ complex, which has a specific affinity for COPA-99AA." (PMID 40723354, 2025). "Our data suggest that glioma and NB cells are less vulnerable to the cytotoxic effect of VV-GMCSF-Lact due to increased expression of the genes of the RAB, DCTN, SEC, and COPA families, which encode the components of Golgi vesicles, protein transport, and secretion." (PMID 37998351, 2023). "Others were robust and shared across most samples such as CD74 receptor binding to MIF, COPA, or APP as cognate ligands and SPP1-CD44 (myeloid to glioma signaling) and TNFRSF1A-GRN, PGRMC2-CCL4L2, MDK-SORL1 or LRP1, and GPR37L1-PSAP (glioma to myeloid signaling)." (PMID 35140215, 2022).
hepatocellular carcinoma (3 papers, 2019 to 2024). A malignant tumor that arises from hepatocytes. "For COPA, I/V editing was detected in the current seven tissues, and its hypoediting is associated with hepatocellular carcinoma pathogenesis in humans." (PMID 30911384, 2019). "For example, high editing of the FLNB and low editing of the COPA are present in hepatocellular carcinoma (HCC)." (PMID 38233935, 2024).
liver cancer (3 papers, 2019 to 2023). An epithelial or non-epithelial malignant neoplasm that arises from the liver. "Of note, A-to-I editing sites in COPA have already been associated with multiple cancer types, including BRCA and liver cancer (HCC)." (PMID 36969056, 2023). "In addition, coatomer protein complex subunit alpha (COPA), another subunit of COPI, is an important paralog of COPB2 and has been reported to be upregulated in tumors relative to paired adjacent nonmalignant tissues in patients with liver cancer." (PMID 33824874, 2021).
mesothelioma (3 papers, 2012 to 2020). A usually malignant and aggressive neoplasm of the mesothelium which is often associated with exposure to asbestos. "Recently, COPA emerged as a target in mesothelioma, therefore identifying COP proteins as potential therapeutic targets for cancer." (PMID 22745748, 2012). "Likewise, Sudo et al19 found the involvement of COPA and COPB2 during cellular growth as well as during apoptosis of mesothelioma cells in vitro." (PMID 31119859, 2019).
prostate carcinoma (3 papers, 2019 to 2023). A carcinoma that arises from epithelial cells of the prostate gland. "Downregulation of intracellular COPA levels has been shown to dramatically reduce tumorigenic ability of hepatocarcinoma cells and inhibit the proliferation of prostate cancer cells." (PMID 34991628, 2022).
breast carcinoma (2 papers, 2015 to 2023). "Recently, an in vitro study showed that upregulation of COPA increased the vitality of breast cancer cells and promoted their invasion and migration." (PMID 37791813, 2023).
lung disease (2 papers, 2021 to 2024). "This case involved an atypical woman in her 50s who had lung disease classified as RA-ILD, and whose COPA mutation was discovered through sequencing lung transplant recipients." (PMID 39767180, 2024).
STING-associated vasculopathy with onset in infancy (2 papers, 2022 to 2026). "Dysregulated STING activation is also associated with diseases, such as STING-associated vasculopathy with onset in infancy (SAVI) and variations in the coatomer protein complex subunit alpha (COPA) gene." (PMID 35734577, 2022).
acute T-cell lymphoblastic leukemia (1 paper, 2024). "The role of CD74 and COPA in regulating the immunosuppressive microenvironment as well as the function of LGALS9 and HAVCR2 in regulating T-cell responses signified that they may be potential targets for the treatment of acute T-cell lymphoblastic leukemia." (PMID 39422621, 2024).
Aicardi–Goutières syndrome (1 paper, 2024). "The most common T1Is that feature SLE phenotypes comprise DNASE1L3 and DNASEII deficiencies, COPA (coatomer subunit-α) syndrome, Aicardi–Goutières syndrome (AGS), and STING-associated vasculopathy with onset in infancy (SAVI)." (PMID 39135943, 2024).
Alzheimer disease (1 paper, 2022). A progressive, neurodegenerative disease characterized by loss of function and death of nerve cells in several areas of the brain leading to loss of cognitive function such as memory and language. "Previous reports suggested that the interaction between APP, COPA, and CD74 is often associated with neurodegenerative diseases, such as Alzheimer's disease." (PMID 35525962, 2022).
atopic asthma (1 paper, 2015). An asthma that is characterized by symptoms that are triggered by an allergic reaction caused by inhaled allergens such as dust mite allergen, pet dander, pollen and mold. "A GWAS of atopic asthma implicated SNPs that were in linkage disequilibrium with SNPs in COPA, though these did not achieve genome-wide significance." (PMID 26292806, 2015).
bacteremia (1 paper, 2022). "The relative increase in the survival of the ΔcopA and ΔcopA ΔgshT strains, compared with that of the wild-type and ΔgshT strains, respectively, suggests that the loss of CopA may confer a selective advantage in the early stages of bacteremia and meningitis." (PMID 36413018, 2022).
bladder cancer (1 paper, 2025). "Functionally, the deficiency of COPA reduces the proliferation of FGFR‐altered bladder cancer cells upon erdafitinib treatment." (PMID 40112217, 2025). "In this study, we performed genome‐wide CRISPR screen and identified COPA as a critical gene associated with erdafitinib sensitivity in FGFR‐driven bladder cancer." (PMID 40112217, 2025). "The knockout of COPA enhanced the sensitivity of FGFR‐altered bladder cancer cells to erdafitinib, both in vivo and in vitro." (PMID 40112217, 2025). "Remarkably, COPA may serve as a potential therapeutic target to improve the efficacy of erdafitinib therapy for FGFR‐driven bladder cancer patients." (PMID 40112217, 2025). "In conclusion, our study highlights a significant mechanism of erdafitinib resistance and suggests that COPA could serve as a promising target to enhance the sensitivity of erdafitinib treatment in FGFR‐altered bladder cancer." (PMID 40112217, 2025). "Therefore, we speculated that the regulation of COPA on TKI sensitivity may be specific in erdafitinib treatment of bladder cancer." (PMID 40112217, 2025). "First, we performed Co‐IP assay to confirm endogenous binding of COPA, COPB2, COPB1, and COPG in bladder cancer cells." (PMID 40112217, 2025). "Overall, our study highlights the role of COPA in regulating erdafitinib resistance, and provides a promising therapeutic target to enhance the sensitivity of erdafitinib treatment in FGFR‐altered bladder cancer." (PMID 40112217, 2025). "Likewise, COPA and LRPPRC were colocalized in the cytoplasm of bladder cancer cells." (PMID 40112217, 2025).
coinfection (1 paper, 2021). The simultaneous infection of a host by multiple pathogen species. "According to our data set, miR-122-5p is downregulated in HIV/HCV coinfection and modulates the expression of COPA and OSBP." (PMID 34829855, 2021).
cryoglobulinemia (1 paper, 2024). Cryoglobulinemia is a type of vasculitis that is caused by abnormal proteins (antibodies) in the blood called 'cryoglobulins.' At cold temperatures, these proteins become solid or gel-like, which can block blood vessels and cause a variety of health problems. "The finding of a mutation in the COPA gene in sisters with cryoglobulinemia, which is a lymphoproliferative disorder, may therefore indicate a relationship between intracellular disorders and the inappropriate activation of B cells, which requires further research." (PMID 39620212, 2024).
fungal infections (1 paper, 2025). "Mutations in the copper-related gene copA have been found to drastically alter copper tolerance in X. fastidiosa, which is vital for agricultural survival given the frequency of copper in treating fungal infections in the vineyard, a fungicide that has been in use since the eighteenth century." (PMID 40673897, 2025).
influenza (1 paper, 2018). An acute viral infection of the respiratory tract, occurring in isolated cases, in epidemics, or in pandemics; it is caused by serologically different strains of viruses (influenzaviruses) designated A, B, and C, has a 3-day incubation period, and usually lasts for 3 to 10 days. "While RNAi of a single gene (e.g. ATP6AP1, COPA, or ARCN1) inhibited replication of many strains of influenza tested here, there were several endemic strains that were not inhibited, and inhibition of diverse strains (e.g. H7N3, H9N2) was particularly weak in the absence of combinatorial RNAi." (PMID 29775471, 2018).
leukemia (1 paper, 2024). A malignant (clonal) hematologic disorder, involving hematopoietic stem cells and characterized by the presence of primitive or atypical myeloid or lymphoid cells in the bone marrow and the blood. "It is possible that the activation of COPA affects leukemia pathogenesis and progression through immunosuppressive effects." (PMID 39422621, 2024).
lung squamous cell carcinoma (1 paper, 2024). "For lung squamous cell carcinoma, 11 genes were causally related, comprising COPA, NCSTN, U91328.19, GABBR1, IER3, HLA-DQB1-AS1, HLA-DQB2, ANKRD26, PKD2L1, PSMA4 and RAD51C." (PMID 38834983, 2024).
lupus (1 paper, 2026). "Among them, we identified pathogenic or likely pathogenic variants in genes previously associated with monogenic lupus, including a novel C1QA variant as well as other lupus-associated genes (COPA, ADAR, TLR7, IKZF3, RELA, PTPN11, SERPING1)." (PMID 41930824, 2026).
oral squamous cell carcinoma (1 paper, 2022). "Also, CD74-MIF/COPA/APP interactions were expressed in TME of oral squamous cell carcinoma after chemotherapy." (PMID 35784460, 2022).
tumor (23 papers, 2020 to 2025). "Edited COPA acts as a tumor suppressor, while unedited COPA functions as a tumor promoter, indicating dual roles of ADAR2-mediated editing." (PMID 40852728, 2025). "Editing at the I164V site, mediated by ADAR2 binding to intronic editing complementary sequences, transforms COPA from a tumor-promoting to a tumor-suppressing isoform." (PMID 40852728, 2025). "Mechanistically, the edited COPA (COPA^I164V) attenuates tumor growth by suppressing the PI3K/AKT/mTOR pathway via downregulation of Caveolin-1 (CAV1), thereby decreasing mTOR-driven cell proliferation and survival." (PMID 40852728, 2025). "Conversely, ADAR2 demonstrates tumor-suppressive activity via editing of transcripts like COPA, switching its function from oncogenic to suppressive by inhibiting PI3K/AKT/mTOR signaling." (PMID 40852728, 2025). "Recently, COPA was reported involves in a novel carcinogenesis of hepatocarcinoma, a virus-related tumor." (PMID 34991628, 2022). "We found that LGALS9_CD44, MIF_TNFRSF14, CD47_SIRPG, MDK_LRP1 and LGALS9_HAVCR2, CD74_COPA, C3_C3AR1, ANXA1_FPR3 interactions were upregulated in both ductal-tumor and malignant cells versus ductal-normal." (PMID 35087839, 2021). "In contrast, ADAR2 demonstrates a dualistic role: its editing of COPA suppresses tumor progression." (PMID 40852728, 2025). "APP and COPA are suggested to play promoting roles in tumor progression and metastasis." (PMID 37945567, 2023). "Similarly, only EVs released by hypoxic tumours were found to contain the ‘coatomer’ complex of subunits alpha (COPA), beta (COPB1), and epsilon (COPE), which mediate protein cargo transport between the Golgi and endoplasmic reticulum." (PMID 33050615, 2020). "Functional studies with MSTO-211H cell line revealed that the knockdown of COPA gene by siRNA suppressed tumor growth and induced apoptosis in vivo, suggesting that COPA could be a novel therapeutic target in MPM." (PMID 32882916, 2020). "In addition, we aimed to investigate whether COPA is widely involved in regulating the sensitivity of tumor cells to various TKIs." (PMID 40112217, 2025). "It was also reported that reduced editing of COPA was implicated in the pathogenesis of HCC and editing of COPAWT may switch it from a tumor-promoting gene to a tumor suppressor by deactivating the PI3K/AKT/mTOR pathway through downregulation of caveolin-1 (CAV1)." (PMID 33824874, 2021). "For example, ADAR1 promotes tumor progression in melanoma and TNBC by evading the immune system and suppressing IFN signaling, while ADAR2 exhibits tumor-suppressive roles in GBM and liver cancer by editing transcripts such as COPA and CDC14B." (PMID 40852728, 2025). "Exploring receptor-ligand interactions, we observed that aDCs and CD8+T cells primarily collaborated in executing anti-tumor functions through APP|CD74 and COPA|CD74 receptor-ligand pairs." (PMID 38565865, 2024). "Depletion of COPA or COPB2, using two independent shRNAs targeting each gene, impaired the ability of irradiated, senescent fibroblasts to promote the growth of 5PT tumour cells in this setting." (PMID 38012402, 2023). "The results showed that CAFs, tumor cells, and B cells can participate in a series of functional interactions involving CXCL12 receptor-mediated APP, COPA, and MIF signaling." (PMID 37719863, 2023). "Seven genes of the prognostic model (COPA, GPX7, ITGB5, MATN3, MCM7, MMP1, and SPP1) have been validated to be related to tumor progression, whereas the remaining three genes, BNDF, GADD45B, and LOX, need to be further analyzed." (PMID 35699863, 2022). "Based on the results of CellPhoneDB, the CD74-MIF/COPA/APP interactions between B cells, dendritic cells, macrophages and epithelial cells were identified in the residual tumor compared with tumor bed." (PMID 35784460, 2022).